ENSG00000276919
Gene: Miscellaneous RNA gene on chromosome 14 (100,829,350 to 100,829,454, forward strand). Ensembl gene ENSG00000276919.
Gene Ontology:
Biological process: negative regulation of cell growth
Homologues: Orthologues: mouse Gm55096 (76% identical), mouse Gm55207 (76% identical).